SERF1A (small EDRK-rich factor 1A)
Description:
Positive regulator of amyloid protein aggregation and proteotoxicity. Induces conformational changes in amyloid proteins, such as APP, HTT, and SNCA, driving them into compact formations preceding the formation of aggregates.
Synonyms: h4F5; FAM2A; SERF1; SMAM1; 4F5
Tractability: PROTAC: ubiquitination databases record sites on it.
Gene: Protein-coding gene on chromosome 5 (70,900,669 to 70,918,530, forward strand). Ensembl gene ENSG00000172058.
Subcellular location: Cytoplasm, cytosol; Nucleus
Subcellular location (Human Protein Atlas): Nuclear bodies
Gene Ontology:
Molecular function: protein binding
Biological process: amyloid fibril formation; protein destabilization; nervous system development
Cellular component: cytosol; nucleus; protein-containing complex
Homologues: Orthologues: dog SERF1A (95% identical), mouse Serf1 (94% identical), pig SERF1A (94% identical), rat Serf1 (94% identical), guinea pig SERF1A (92% identical), rabbit SERF1A (92% identical). Paralogues in human: SERF1B (65% identical).
Diseases named in the same sentence as SERF1A in open-access papers:
SERF1A is named in the same sentence as 4 diseases in open-access papers, as found by Europe PMC text mining. Sharing a sentence is not in itself a finding about the gene and the disease. The quoted sentences say what the papers report.
Alzheimer disease (1 paper, 2017). A progressive, neurodegenerative disease characterized by loss of function and death of nerve cells in several areas of the brain leading to loss of cognitive function such as memory and language. "A study of ceRNAs in the Alzheimer’s disease showed that BACEl-AS (BACEl-antisense, BACEl-AS) could be an endogenous competitive RNA to target miRNA (mir01273, mir-1285, and mir-3064) and activate the transcription of SERFla (small EDRK-rich factor 1A, SERF1a)." (PMID 28587591, 2017).
breast carcinoma (1 paper, 2013). "We developed a prognostic tool for early breast cancer based on the analysis of the relative expression level of FGF18, BCL2, PRC1, MMP9 and SERF1A in combination." (PMID 23648477, 2013).
neuroblastoma (1 paper, 2023). Neuroblastoma (NB) is the most common solid, extracranial childhood tumor. "The results further validated that SERF1a promotes Httex1-polyQ aggregation and cytotoxicity in human neuroblastoma and induces significantly higher aggregation in HD iPSC-derived neurons than in healthy control." (PMID 37479809, 2023). "Co-expression of SERF1a and Httex1-polyQ in neuroblastoma and lentiviral infection of SERF1a in HD-induced polypotent stem cell (iPSC)-derived neurons demonstrates the detrimental effect of SERF1a in HD." (PMID 37479809, 2023). "To determine whether the aggregation and toxicity of Htt exon 1 arise from SERF1a in cells, we co-expressed EGFP-tagged Htt exon 1 with 25Q (EGFP-Httex1-25Q) or 109Q (EGFP-Httex1-109Q) and SERF1a-myc or myc-only plasmids in mouse neuroblastoma Neuro-2A and subjected to fluorescence microscopy." (PMID 37479809, 2023).
neurodegenerative disease (2 papers, 2023 to 2024). A disorder of the central nervous system characterized by gradual and progressive loss of neural tissue and neurologic function. "Given that SERF1a is a general modifier for amyloid formation, elucidating SERF1a structure and function is important for understanding neurodegenerative diseases." (PMID 37479809, 2023).